PDPN (podoplanin)
Diseases named in the same sentence as PDPN in open-access papers (continued):
Sharing a sentence is not in itself a finding about the gene and the disease.
cyst (6 papers, 2013 to 2024). A sac-like closed membranous structure that may be empty or contain fluid or amorphous material. "Pathological examination found that the immunostaining revealed that the lining cell inside the cyst was positive for calretinin and podoplanin (D2-40)." (PMID 39113815, 2024). "Pathological examination found that the immunostaining showed that the lining cells within the cyst were positive for calretinin and podoplanin (D2-40)." (PMID 39113815, 2024). "In our patient, the cyst-lining cells were positive for podoplanin and the stromal cells were positive for estrogen receptors." (PMID 29262869, 2017). "In this case of an endometriosis-associated hydrocele of the canal of Nuck, the mesothelial origin of the cyst-lining cells and endometriosis were confirmed by positive immunohistochemical staining for podoplanin and estrogen receptors, respectively." (PMID 29262869, 2017). "Immunohistochemical analysis using immunoperoxidase stain with hematoxylin counterstain revealed that the cyst-lining cells were positive for podoplanin (D2-40)." (PMID 29262869, 2017). "Immunohistochemical staining for podoplanin confirmed the mesothelial origin of the cyst-lining cells." (PMID 29262869, 2017). "Of the remaining immunostains employed, D2-40 (podoplanin) was found to be the most useful for highlighting the synovial lining of the cyst; it clearly marked the entire inner contour of the cyst, excluding the possible existence of a ganglion cyst." (PMID 23573446, 2013). "Besides, a significant relationshipwas found between podoplanin expression and the type of cyst (p= 0.002)." (PMID 38962078, 2024). "The expression of podoplanin in the epithelial cells of two cyst groups was also examined." (PMID 38962078, 2024). "In the present study, the high podoplanin expression was observed in the parabasal and basal layers of OKC, which indicates the high proliferative activity of these cells, their capacity for intrinsic growth, and local invasiveness of the cyst." (PMID 38962078, 2024). "Immunohistochemical staining including factor VIII, podoplanin, endothelial markers (CD31, CD34, ERG avian V‐ets erythroblastosis virus E26 oncogene homolog), FLI1 (“friend leukemia factor”), and matrix metalloproteinase‐1 (MMP-1) can help to identify cAS in the cyst walls." (PMID 35543776, 2023).
diabetes (6 papers, 2008 to 2025). "In diabetes, poor tissue regeneration and chronic edema are associated with chronic inflammation and lymphatic dysfunction, which result from the decreased expression of podoplanin." (PMID 41465476, 2025). "Additionally, podoplanin expression may alter platelet function in diabetes, leading to an increased risk of microvascular thrombosis." (PMID 41465476, 2025). "The role of PDPN in diabetes has been investigated as it contributes to diabetic kidney disease and islet fibrosis." (PMID 41465476, 2025). "In diabetes, wound healing is impaired, due to decreased numbers of macrophages (F4/80+, Lyve-1+, podoplanin+) and lymph vessels." (PMID 18430230, 2008).
hemangioma (6 papers, 2015 to 2026). A benign vascular lesion characterized by the formation of capillary-sized or cavernous vascular channels. "This co-expression pattern distinguishes AS from hemangiomas, which is consistently negative for PDPN." (PMID 40666093, 2025).
osteoarthritis (6 papers, 2011 to 2022). A noninflammatory degenerative joint disease occurring chiefly in older persons, characterized by degeneration of the articular cartilage, hypertrophy of bone at the margins and changes in the synovial membrane. "We examined expression patterns of the glycoprotein E11/podoplanin by immunohistochemical labelling in murine, human and canine osteoarthritis models." (PMID 31351471, 2019). "Podoplanin expression in human synovial tissue from 18 RA patients and nine osteoarthritis (OA) patients was assessed by immunohistochemistry and confirmed by Western blot analysis." (PMID 21385358, 2011). "Human skeletal stem cells (hSSCs) were recently identified as podoplanin (PDPN)/CD73/CD164-positive and CD146-negative cells that decline with age, and play a role in the pathogenesis of osteoarthritis (OA)." (PMID 35743928, 2022). "Both podoplanin and FAP are known to be involved in EMT and are reported to be highly expressed in cells of the intimal lining layer in RA, with little expression in osteoarthritis synovium." (PMID 28793332, 2017). "In this regard, it is worth mentioning that a previous work noticed an expansion of a fibroblast population expressing podoplanin, CD90/Thy1 and cadherin‐11, but lacking CD34, in patients with RA relative to patients with osteoarthritis." (PMID 33350073, 2021). "One fibroblast subset, characterized by the expression of proteins podoplanin, THY1 membrane glycoprotein and cadherin-11, but lacking CD34, is threefold expanded in patients with RA relative to patients with osteoarthritis." (PMID 29476097, 2018).
psoriasis (6 papers, 2019 to 2023). An autoimmune condition characterized by red, well-delineated plaques with silvery scales that are usually on the extensor surfaces and scalp. "Dermal fibroblast-like cellsand basal epidermal keratinocytes have high PDPN in hyper-proliferative conditions such as psoriasis, wound healing, or in response toinflammatory stimuli." (PMID 38415034, 2023). "In psoriasis, podoplanin is expressed in peripheral basal keratinocytes, particularly in highly proliferative lesions lacking a granular layer." (PMID 35163233, 2022). "Podoplanin is involved in both keratinocyte proliferation and inflammation during the pathogenesis of psoriasis because it is expressed in keratinocytes and inflammatory cells such as monocytes and Th17 cells." (PMID 35163233, 2022). "Recent studies have also indicated that podoplanin contributes toward IL-17 secretion in inflammatory skin diseases, such as psoriasis." (PMID 35163233, 2022). "In psoriasis, podoplanin expression is induced in basal keratinocytes via the JAK-STAT pathway and contributes toward epidermal hyperproliferation." (PMID 35163233, 2022). "Mouse basal keratinocytes and dermal fibroblasts upregulate podoplanin expression under proliferative conditions, such as wound healing, psoriasis and phorbol ester 12-O-tetradecanoylphorbol 13-acetate (TPA)-induced inflammation." (PMID 32599908, 2020). "In fact, podoplanin-positive T cells distinct from IL-17-positive T cells were identified in the skin lymphocytic infiltrates of patients with candidiasis and psoriasis." (PMID 30736372, 2019). "Although induction of podoplanin expression correlates with hyperproliferation in the epidermis during psoriasis and wound healing, it is likely that its function in keratinocytes is related to cell migration rather than proliferation." (PMID 30736372, 2019). "Atransmembrane glycoprotein of the mucin type, PDPN is found extensively in various tissues and cells.PDPN is elevated in dermal fibroblast-like cells and basal epidermal keratinocytes inhyperproliferative situations like psoriasis, healing of wounds, or in response to stimuli to inflammation." (PMID 38415034, 2023). "Furthermore, IL-22 and IL-6, which play key roles in the pathological mechanism of psoriasis, also induce podoplanin expression via STAT-3 phosphorylation." (PMID 35163233, 2022). "In addition to stimulation with TPA, the expression of podoplanin is induced in basal epidermal keratinocytes and dermal fibroblast-like cells during wound healing and psoriasis." (PMID 33003440, 2020). "A role for podoplanin in mediating interactions between activated immune cells and dermal fibroblasts derived from inflamed skin for secretion of IL-17 was also proposed in psoriasis." (PMID 30736372, 2019). "In psoriasis, the effects of podoplanin on Th17 inflammation are controversial and further studies are required to elucidate the podoplanin-mediated cellular pathways that affect immune responses and, thus, the functional roles of podoplanin during the pathogenesis of psoriasis." (PMID 35163233, 2022).
thyroid cancer (6 papers, 2014 to 2024). "The expression of both the RP11-474O21.5 (GEPIA database) and PDPN is increased in thyroid carcinoma." (PMID 35216288, 2022). "We demonstrate that PDPN knock-down either promote or suppress metastatic potential of thyroid cancer cell depending on the genetic background." (PMID 30654768, 2019). "The aim of this study was to determine the effect of PDPN down-regulation in another thyroid cancer-derived cell line: BcPAP." (PMID 30654768, 2019). "The effect of PDPN silencing on the motility of thyroid cancer cells (TPC1 and BcPAP) was investigated using a classical wound healing assay and a chamber migration assay." (PMID 30654768, 2019). "The functional analysis of PDPN in TPC1 cells suggested that it has a pro-metastatic activity also in thyroid cancer, enhancing invasiveness of malignant thyroid cells." (PMID 30654768, 2019). "We observed that the inhibition of the MAPK pathway resulted in decreased levels of PDPN expression in both studied thyroid cancer cell lines." (PMID 30654768, 2019). "Our findings in thyroid cancer cells show that PDPN-induced changes of the tumor microenvironment promoted thyroid tumor cell motility, invasion, and metastasis." (PMID 30654768, 2019). "RT-qPCR analyses demonstrated that siPDPN efficiently decreases PDPN levels 48 h after transfection in both thyroid cancer cell lines." (PMID 30654768, 2019). "To corroborate the RT-qPCR results, we carried out Western blotting and immunfluorescence analyses to evaluate PDPN protein expression and determine its cellular localization in thyroid cancer cell lines." (PMID 24797369, 2014). "The purpose of this study was to elucidate the molecular role of PDPN in the biology of thyroid cancer cells." (PMID 24797369, 2014). "PDPN expression was examined in primary tumors and in a panel of thyroid cancer cell lines derived from papillary (TPC1 and BcPAP) and follicular (FTC133 and CGTH-W-1) thyroid carcinomas." (PMID 24797369, 2014). "Here we examined the potential role of podoplanin, a lymphangiogenic factor, in regulating the spread of thyroid cancer cells." (PMID 24797369, 2014). "The molecular mechanisms by which PDPN can affect the metastatic phenotype of the thyroid cancer cells have yet to be revealed." (PMID 24797369, 2014). "To examine the role of podoplanin in thyroid cancer biology we investigated the expression profile of the PDPN transcript and protein in a series of DTC tissues and in papillary and follicular DTC-derived cell lines." (PMID 24797369, 2014). "We also examined the role of PDPN in promoting motility, migration and invasiveness of thyroid carcinoma cells." (PMID 24797369, 2014). "PDPN expression was evaluated in primary thyroid carcinomas and thyroid carcinoma cell lines by RT-qPCR, Western blotting, IF and IHC." (PMID 24797369, 2014). "In the thyroid carcinoma cells, remarkable differences in the relative PDPN transcript level between cells originating from PTC and FTC were observed." (PMID 24797369, 2014). "Further studies are necessary to elucidate the detailed mechanism/s by which PDPN expression is regulated in differentiated thyroid carcinoma cells and contributes to metastatic potential of thyroid tumors." (PMID 24797369, 2014). "TPC1 and BcPAP cells exhibited the highest level of PDPN mRNA expression among all the tested thyroid carcinoma cell lines." (PMID 24797369, 2014). "The observed differences in PDPN expression in thyroid cancer cells might be due to the presence of known genetic alterations in PTC cells." (PMID 24797369, 2014). "In summary, this is the first evaluation of the expression and function of podoplanin in thyroid cancer, and our results strongly suggest that the malignant potential of PTCs may be related to PDPN expression." (PMID 24797369, 2014). "The expression of PDPN is slightly different to the expression of thyroid transcription factor-1 (TTF-1), a marker for thyroid carcinoma." (PMID 29100400, 2017).
thyroid cancer (continued). "To investigate the functional role of podoplanin in thyroid cell biology we examined a normal thyroid cell line (NTHY), and a panel of papillary (TPC1 and BcPAP) and follicular (FTC133 and CGTH-W-1) thyroid cancer-derived cell lines." (PMID 24797369, 2014).
astrocytomas (5 papers, 2011 to 2025). "Lung type I cell membrane-associated glycoprotein, also known as podoplanin, has been implicated in promoting invasion of astrocytomas; its expression also declines following STAT6 knockdown in U-87MG." (PMID 21595984, 2011). "Furthermore, PDPN expression increased from 70% in low-intermediate-grade astrocytomas to 87% in high-grade astrocytomas (GBMs)." (PMID 36059614, 2022).
colitis (5 papers, 2016 to 2025). Inflammation of the colon. "Compared to the NC rats, the expression of podoplanin was increased in the mesenteric lymphatics of DSS-induced colitis rats." (PMID 38785804, 2024). "In the colitis model, IL-11+ fibroblasts exclusively expressed stromal cell markers, such as Thy1 and podoplanin." (PMID 33863879, 2021).
epithelioid mesothelioma (5 papers, 2006 to 2026). "The positive rate of PDPN staining was 86.7% (13/15) in epithelioid mesothelioma and 66.7% (2/3) in biphasic mesothelioma." (PMID 32326079, 2020). "Additional markers used for epithelioid mesothelioma diagnosis include positive podoplanin (D2-40) and negative MOC-31, which were also noted in the patient’s pathology." (PMID 36171577, 2022).
fibrosarcoma (5 papers, 2017 to 2023). A malignant mesenchymal fibroblastic neoplasm affecting the soft tissue and bone. "The TGF-β–Smad pathway was also found to stimulate podoplanin expression in fibrosarcoma cells." (PMID 30736372, 2019). "Similarly, ectopic expression of CD9 in fibrosarcoma cell line HT1080 reduced their lung metastatic ability by forming a complex with podoplanin, suppressing podoplanin-induced platelet aggregation." (PMID 37007105, 2023). "Finally, CD9 tetraspanin prevented the podoplanin–CLEC-2 interaction and inhibited platelet aggregation and metastasis of fibrosarcoma cells." (PMID 30736372, 2019). "CD44 is not the only partner known to interact with podoplanin through the TM region, since tetraspanin CD9, which has four TM domains, was reported to bind podoplanin through TM domains 1 and 2 in fibrosarcoma cells." (PMID 33003440, 2020).
invasive carcinoma (5 papers, 2010 to 2025). A carcinoma that is not confined to the epithelium, and has spread to the surrounding stroma. "Further studies with larger sample size and follow up may elucidate the exact role of biomarkers like podoplanin in PMDs and invasive carcinoma." (PMID 29410757, 2017).
multiple sclerosis (5 papers, 2015 to 2021). A progressive autoimmune disorder affecting the central nervous system resulting in demyelination. "A postmortem study showed increased expression of podoplanin in the inflamed cerebrum of multiple sclerosis patients." (PMID 30736372, 2019). "Furthermore, podoplanin is overexpressed in the inflamed brain tissues of multiple sclerosis patients, indicating a specific role of podoplanin/CLEC-2 signaling in neuroinflammation." (PMID 34177942, 2021).
myocardial infarction (5 papers, 2020 to 2026). Gross necrosis of the myocardium, as a result of interruption of the blood supply to the area, as in coronary thrombosis. "However, an acknowledged major role for PDPN is to mediate cell migration in several contexts, including keratinocyte, cancer-associated fibroblast, mesenchymal stem cell, and myocardial infarction-activated fibroblast migration." (PMID 37298679, 2023). "Following myocardial infarction (MI), PDPN expression expands beyond its typical localization, appearing in a heterogeneous population of progenitor cells." (PMID 41562845, 2026). "Previous reports indicated that a high frequency of podoplanin-expressing cells appeared in the infarcted heart and facilitated local inflammation, and podoplanin neutralization improved cardiac function after myocardial infarction." (PMID 33200983, 2020). "In addition, studies show that podoplanin is a marker of myocardial injury, and inhibition of podoplanin can accelerate recovery after myocardial infarction." (PMID 34177942, 2021).
non-small cell lung carcinoma (5 papers, 2010 to 2024). A group of at least three distinct histological types of lung cancer, including non-small cell squamous cell carcinoma, adenocarcinoma, and large cell carcinoma. "Additionally, soluble PDPN levels in plasma samples of non-small cell lung carcinoma patients were elevated in comparison to healthy individuals." (PMID 40741180, 2024).
prostate carcinoma (5 papers, 2007 to 2023). A carcinoma that arises from epithelial cells of the prostate gland. "In contrast, expression of podoplanin has not been found in the majority of adenocarcinomas, including lung, colon and prostate cancers." (PMID 17179989, 2007).
testicular seminoma (5 papers, 2018 to 2024). A malignant germ cell tumor arising from the testis. "PDPN is highly expressed in testicular seminoma, suggesting that it may be a sensitive marker for testicular seminomas." (PMID 39682237, 2024).
astrocytic tumor (4 papers, 2007 to 2024). A glial tumor of the brain or spinal cord showing astrocytic differentiation. "Previous studies have demonstrated that PDPN, a sialoglycoprotein found in the cell membrane and encoded by the PDPN gene, is upregulated and linked to cellular invasion in astrocytic tumors, although the regulatory mechanisms remain unknown." (PMID 39682237, 2024). "An investigation into the expression of PDPN in astrocytic tumors found that PDPN was present on the surface of anaplastic astrocytoma cells and GBM cells, particularly around necrotic areas and proliferating endothelial cells." (PMID 39682237, 2024). "Aquaporin 4 is the major water channel in the brain, expressed predominantly in astroglial cells, and plays a major role in fluid clearance in vasogenic brain edema, whereas podoplanin is a lymphatic endothelial cell marker and has been reported to be upregulated in astrocytic tumors." (PMID 18021406, 2007).
Cerebral ischemia (4 papers, 2021 to 2024). Restriction of arterial blood supply to the brain associated with insufficient oxygenation to support the metabolic requirements of the tissue. "RhoA/ROCK signaling pathway in astrocytes is suggested to be crucial in neurogenesis and angiogenesis after cerebral ischemia, which indicates the crosstalk among podoplanin, ERM protein family, and astrocytes in ischemic stroke needs to be further studied." (PMID 36970507, 2023). "Podoplanin inhibitors mitigated the pathological changes after cerebral ischemia-reperfusion in a mouse model of middle cerebral artery occlusion-induced stroke, which indicates a potential role of the CLEC-2/podoplanin axis in thromboinflammation." (PMID 34177942, 2021).